SIRT1 (sirtuin 1)
Diseases named in the same sentence as SIRT1 in open-access papers (continued):
Sharing a sentence is not in itself a finding about the gene and the disease.
type 2 diabetes (continued). "Among the identified mammalian sirtuins (SIRT1–7), SIRT1 has been shown to have critical functions in the prevention of many age-related diseases in mice models, such as type 2 diabetes, neurodegeneration, cancer, and Alzheimer′s disease." (PMID 33608631, 2021). "SIRT1 is a vital regulator in age-related diseases, such as type 2 diabetes and Alzheimer’s disease." (PMID 33942704, 2021). "Type 2 diabetes is characterized by suppression of SIRT1 and AMPK signaling as well as an impairment of autophagy; these derangements contribute to an increase in oxidative stress and the development of cardiomyopathy." (PMID 32404204, 2020). "Only limited and unfocused reports about cinnamon’s therapeutic value on NF-kB, SIRT1 and systemic inflammation factors exist to date, in type 2 diabetes patients." (PMID 31901246, 2020). "As an NAD+-dependent histone deacetylase, SIRT1 is extensively studied in several senile diseases including type 2 diabetes, cardiovascular diseases, cancers, age-related macular degeneration, and neurodegenerative diseases." (PMID 32922581, 2020). "Type 2 diabetes is accompanied by a decrease in the activation of SIRT1 and AMPK and by a striking suppression of autophagy; these changes have been implicated in the myocardial injury and cardiomyopathy in type 2 diabetes." (PMID 32404204, 2020). "The aim was to assess the effects of vitamin D supplementation on SIRT1, irisin, and IR in overweight/obese type 2 diabetes (T2D) patients." (PMID 32033527, 2020). "Recent research studies illustrate that SIRT1 alleviates neuropathic pain induced by type 2 diabetes, Freund's adjuvant, bortezomib, paclitaxel, or chronic constriction injury (CCI) in the spinal cord and dorsal root ganglion." (PMID 32922581, 2020). "Up to date, no similar study has been performed regard to cinnamon supplementation effects on NF-kB and SIRT1 in type 2 diabetes patients to compare with our results." (PMID 31901246, 2020). "There is also evidence that SIRT1 mRNA and protein levels are decreased in conditions of energy excess, including Type 2 diabetes and obesity." (PMID 30890694, 2019). "Of the seven human sirtuin isoforms, SIRT1 is of the most interest because it confers healthy ageing by protecting against or delaying the onset of pathologies including Type 2 diabetes, the metabolic syndrome and Alzheimer’s disease." (PMID 31746335, 2019). "In conclusion, moderate exercise training inhibits NFκB signaling and activates SIRT1-AMPKα-PGC1α axis, thereby attenuating type 2 diabetes-related muscle atrophy." (PMID 29896118, 2018). "The relationship between AT SIRT1 and indirect indices of insulin sensitivity and the values from the clamp study in subjects with a family history of type 2 diabetes was also observed by other researchers." (PMID 29417372, 2018). "Although compelling evidence indicates that Sirtuin 1 (SIRT1) plays a prominent role in type 2 diabetes, its relationship with gestational diabetes (GDM) remains elusive." (PMID 30513672, 2018). "An association between single nucleotide polymorphisms within SIRT1 gene and DKD was observed in Japanese subjects with type 2 diabetes." (PMID 30386303, 2018). "Transcriptional profiling revealed that mRNA expression of HDAC3 was significantly (p < 0.05) increased while the Sirt1 level was significantly (p < 0.05) decreased in patients with type 2 diabetes compared to control subjects." (PMID 30139387, 2018). "Consistent with the protective role of Sirt1 (class III HDAC) demonstrated in the literature, Sirt1 mRNA levels were significantly decreased in PBMCs from patients with type 2 diabetes." (PMID 27904654, 2016).
type 2 diabetes (continued). "Silencing the expression of SIRT-1 was demonstrated to result in insulin resistance, type 2 diabetes mellitus (T2DM), and dyslipidemias, which are all recognized adverse effects of atypical APDs." (PMID 27630617, 2016). "Our study indicated that mRNA and protein expression of myocardial SIRT1 were significantly decreased in HFD-STZ-induced type 2 diabetic rats." (PMID 26489513, 2015). "Resveratrol was reported to be a SIRT1 activator and has been shown to protect against type 2 diabetes, cancer, heart disease, inflammation, and neurodegenerative diseases." (PMID 26273643, 2015). "Until now, associations of genetic polymorphisms at SIRT1 and FOXO1 with body mass index (BMI), visceral obesity, insulin sensitivity, type 2 diabetes mellitus (T2DM) and all-cause mortality risk have been described." (PMID 25273948, 2014). "MiR-486-5p regulates the expression of silent information regulator 1 (SIRT1), and SIRT1 expression is correlated with insulin sensitivity and energy expenditure in type 2 diabetic patients." (PMID 24497980, 2014). "The increase of SIRT1 expression and/or activity has positive effects in type 2 diabetes, cancer, cardiovascular diseases, COPD and Alzheimer’s disease." (PMID 23989608, 2013). "SIRT1 is considered to be a possible target for the treament of type 2 diabetes and metabolic syndrome." (PMID 23226517, 2012). "We are reporting results of the first clinical study in elderly volunteers with SRT2104, a compound belonging to a series of novel SIRT1 activators being developed for the treatment of type II diabetes and other-age related diseases." (PMID 23284689, 2012). "SIRT1 has been suggested as putative therapeutic target in multiple age-related diseases including type 2 diabetes and dyslipidemias." (PMID 23284689, 2012). "DR exerted anti-inflammatory effects and improved the dysregulation of autophagy through the restoration of Sirt1 in the kidneys of WFRs, which resulted in the amelioration of renal injuries in type 2 diabetes." (PMID 21949662, 2011). "Taken together these results are encouraging regarding the use of small molecule activators of SIRT1 for therapeutic intervention into type 2 diabetes, a strategy which is currently being investigated in multiple clinical trials." (PMID 19284563, 2009). "Additionally, Garcia Martínez and collaborators showed in a randomized controlled trial the impact of resveratrol supplementation on oxidative stress markers and sirtuin 1 levels in older adults with type 2 diabetes." (PMID 40563357, 2025). "Moreover, it has been observed that patients affected by both coronary artery disease and type 2 diabetes show an inverse correlation between the increase in inflammatory cytokines and SIRT1 upregulation in peripheral blood mononuclear cells." (PMID 41228388, 2025). "According to a study, formononetin may improve neuropathic symptoms in type 2 diabetic rats by boosting the expression of SIRT1 (Sirtuin 1) and NGF in diabetic animals." (PMID 40205269, 2025). "Type 2 diabetes brings multiple complications in the clinic, the most common of which are vascular complications, including diabetic nephropathy, diabetic neuropathy, and more, most of which are affiliated with inactivated SIRT1." (PMID 38799172, 2024). "The SIRT1 mRNA level was significantly reduced in type 2 diabetes comorbid depression patients." (PMID 39612426, 2024). "In other studies, Oza assessed the SIRT1 stimulatory properties of FMNT to kidney damage and neuropathy in type 2 diabetes rats, and spotted that the low expression of SIRT1 was observably reversed after administration with FMNT for 16 weeks (Oza and Kulkarni, 2019; 2020)." (PMID 38799172, 2024). "Regarding the role of the SIRT1 gene in the occurrence of depression, studies pointed out that it might play an important role in the development of the disease, but its role in type 2 diabetes comorbid depression required in-depth study." (PMID 39612426, 2024).
type 2 diabetes (continued). "In summary, resveratrol facilitates TSC2 recruitment to the lysosome, inhibiting mTORC1 pathway and improving the mitochondrial turnover, contributing to pancreatic β cell homeostasis in a TSC2 and SIRT-1 dependent manner, which is crucial in avoiding metabolic disorders such as type 2 diabetes." (PMID 38822085, 2024). "Importantly, SIRT1 and AMPK regulate each other’s activities, an imbalance in which is implicated in human diseases, such as cardiovascular disease, type 2 diabetes, inflammatory disease, and cancer." (PMID 36362370, 2022). "Interestingly, a recent study reported that resveratrol protected against DKD in an AMPK/SIRT1-independent pathway in db/db mouse models of type 2 diabetes." (PMID 35277012, 2022). "Resveratrol, contained in grapes and skin of peanuts, is used already as a dietary supplement and is known to have a beneficial effect on cancer, type 2 diabetes, and cardiovascular disease, owing to the activation of SIRT1 and its protective antioxidant properties." (PMID 33500490, 2021). "Also, administering 180 mg of EA for eight weeks significantly increased SIRT1 and reduced Fetuin-A in patients with type 2 diabetes." (PMID 33546744, 2021). "SIRT1 is known to be susceptible to intracellular fluctuations in the NAD+/NADH ratio and may influence type 2 diabetes risk through its known epigenetic effects and β-cell apoptosis." (PMID 33435147, 2021). "Fourthly, curcumin also enhanced Akt phosphorylation and inhibited Foxo1 acetylation, indicating that it might reduce OS damage of type 2 diabetes and protect cardiomyocyte from apoptosis by modulating Sirt1‐Foxo1and PI3K‐Akt pathways." (PMID 32961025, 2020). "Thus, the expression levels of SIRT1 mRNA were determined in the serum of 15 patients with type 2 diabetes." (PMID 32627000, 2020). "Early study conducted in patients with type 2 diabetes also demonstrated the association of SIRT1 gene and DBP, but not other type 2 diabetes–related traits." (PMID 33324265, 2020). "SRT2183 was originally documented as an activator of Sirt1 for the treatment of type- 2 diabetes." (PMID 31319814, 2019). "In contrast, the effects of SIRT1 activation in Type 1 diabetes, a disease that unlike type 2 diabetes is characterized by ß-cell loss and insulinopenia, has not been previously investigated outside of its potential role in autoimmunity." (PMID 30228292, 2018). "Individuals with type 2 diabetes had lower muscle SIRT1 protein compared to control subjects." (PMID 29417372, 2018). "Interestingly, mRNA expression of Sirt1 and telomere length were significantly (p < 0.05) decreased in patients with type 2 diabetes compared to control subjects." (PMID 30139387, 2018). "Based on these facts it has been hypothesized that formononetin may provide beneficial effect in type 2 diabetes mellitus partly by activating SIRT1." (PMID 30072892, 2018). "Moreover, AMPK and SIRT1 are clinically relevant in metabolic syndrome and type 2 diabetes because their effects on target molecules lead to mitochondrial dysfunction and oxidative damage." (PMID 29238727, 2017). "This study demonstrates that the key metabolic activities of SIRT1 have been conserved through evolution, provides a genetic model for functional studies of phenotypes related to type 2 diabetes, and establishes HNF4 as a critical downstream target by which Sir2 maintains metabolic health." (PMID 27058248, 2016). "In conclusion, we demonstrate, that circadian components of the molecular clock, namely REVERBA/B, SIRT1 and NAMPT, that are associated with mitochondrial function and metabolic health, showed lack of circadian rhythmicity in human primary myotubes from type 2 diabetic patients." (PMID 27756900, 2016).
type 2 diabetes (continued). "Thus, some positive effects of resveratrol in activation of SirT1 protein included age related disorders, as type 2 diabetes, cardiovascular disease, neurodegeneration, and inflammation." (PMID 26284371, 2015). "The function of sirtuin 1 (SIRT1) has been well studied, and activation of SIRT1 may be beneficial in age-related disorders such as type 2 diabetes and neurodegenerative diseases." (PMID 25360511, 2014). "Further studies will be required to explore possible lipid lowering effects of SIRT1 activators in patients with type II diabetes and dyslipidemia, in whom the major targets for therapeutic modulation by SIRT1 may need to be different." (PMID 23284689, 2012). "Likewise, resveratrol and assimilated SIRT1 activators have been proposed as potential treatments for type 2 diabetes in mice models." (PMID 20569453, 2010). "A recent study demonstrated that 8 weeks of aerobic exercise (30–50 min/day, six times/week for 8 weeks) improved renal interstitial fibrosis in type 2 diabetes (T2DM) mice by inhibiting the TGF-β1/Smad3 pathway through the upregulation of Sirt1 expression." (PMID 39796197, 2025). "Thus, the P. frutescens leaf polysaccharide could improve type 2 diabetes-induced rat liver injury by inhibiting oxidative stress and inflammation, while regulating activation of the SIRT1/FoxO1 signaling pathway." (PMID 38585610, 2024). "Interestingly, SIRT1 is a target of metformin, a medication for type 2 diabetes that has also been hypothesized to have preventive effects on AD progression." (PMID 37728850, 2024). "However, the specific relationship between the SIRT1 gene and type 2 diabetes comorbid depression remains unclear." (PMID 39612426, 2024). "Resveratrol, one of the most extensively studied SIRT1 activators, has been studied for its potential to treat type 2 diabetes(T2D)." (PMID 36815979, 2023). "Interestingly, recent studies showed that inhibitors of the sodium-glucose cotransporter-2, used in the therapy of type 2 diabetes, have cardioprotective effects in heart failure related to the systemic activation of SIRT1 and probably to the induction of SIRT1 expression in the heart." (PMID 34356841, 2021). "Interestingly, the energy surplus in type 2 diabetes may not only lead to the suppression of low-energy sensors, but changes in SIRT1, AMPK, HIF-1α and HIF-2α signaling may also contribute to glucose intolerance." (PMID 32404204, 2020). "While SIRT1 is significantly associated with atherosclerosis and diabetic complications, its relevance to coronary lesions in patients with coronary artery disease and type 2 diabetes has not been specifically investigated." (PMID 27123454, 2016). "Interestingly, in comparison to cultures of healthy donors REVERBA and REVERBB analysis showed no circadian rhythmicity in human primary myotubes derived from type 2 diabetes patients, and rhythmicity for SIRT1 and NAMPT was only observed in myotubes from endurance trained athletes." (PMID 27756900, 2016). "The SIRT1 tagging SNPs (rs7895833 A/G, rs1467568 A/G, and rs497849 G/A) were also assessed in the Rotterdam Study cohort (4573 individuals, among them 413 were diagnosed with T2DM and 378 developed T2DM during the follow-up) for their association with type 2 diabetes." (PMID 27104517, 2016). "Therefore, Sirt1 may be a significant therapeutic target for the prevention of nephropathy in type 2 diabetes." (PMID 21949662, 2011). "Therefore, SIRT1 should be elucidated in other prospective lifestyle intervention studies, and further research on SIRT1 as a potential pharmacological target for prevention of type 2 diabetes is warranted." (PMID 19014491, 2008). "Although resveratrol could improve mitochondrial function and plays a role in diseases such as type 2 diabetes and metabolic syndrome in cell lines and animal experiments, previous studies also reported that resveratrol could not robustly extend life span in model organisms through activating SIRT1." (PMID 36552538, 2022).
type 2 diabetes (continued). "Among a series of longevity-related pathways, SIRT1 and SIRT7 were downregulated in myeloid cells of individuals with type 2 diabetes and CCs, but only SIRT7 showed clear relationships with the extent of calcification and with MCC levels." (PMID 35708762, 2022). "There was a significant increase in the level of microRNAs corresponding to SIRT-1, 2, 3 and SIRT-5 for type I diabetes and for SIRT-1, 2 for type II diabetes, respectively." (PMID 36552655, 2022). "Resveratrol can regulate SIRT1 and FOXO1, improve islet function, and reduce blood glucose levels in macaques with type 2 diabetes." (PMID 35685602, 2022). "Pancreatic β-cell dysfunction is a key link during the progression of type 2 diabetes (T2DM), and SIRT1 participates in the regulation of various physiological activities of islet β-cells." (PMID 34630099, 2021). "It has been reported that glycyrrhizic acid ameliorates HG-induced low expression and activity of AMPK, Sirt1, and SOD2 in renal tubular cells and improves DKD in a mouse model of type 2 diabetes by suppressing ROS and activating the AMPK/Sirt1 pathway." (PMID 34439446, 2021). "It has been explored that in type 2 diabetes, AGE-RAGE signaling inhibited SIRT1 expression and subsequently downregulation of Nrf2 and downstream antioxidant genes." (PMID 33468193, 2021). "In an intervention trial with patients suffering from type 2 diabetes (T2D), CR-like properties were shown by resveratrol treatment, with activation of AMPK and SIRT1 in the muscle biopsies." (PMID 34552954, 2021). "Our purpose was to evaluate the effect of cinnamon supplementation on NF-kB, SIRT1 and systemic inflammation factors (hs-CRP, IL-6 and TNF-α) levels among type 2 diabetes patients." (PMID 31901246, 2020). "This study is aimed at establishing models of obese type 2 diabetes in vitro and in vivo, observe the effect of MNAM on hepatic insulin sensitivity and glucose metabolism, and explore the regulation of the SIRT1/FOXO1 pathway." (PMID 32280711, 2020). "For example, in a model of diet-induced type 2 diabetes, NMN restored insulin signaling and ameliorated oxidative stress and inflammation by activating Sirtuin 1 (SIRT1)." (PMID 31823815, 2019). "Together, these studies clearly demonstrate a protective role of SIRT1 against DKD in experimental models of both type 1 and type 2 diabetes." (PMID 30386303, 2018). "The aims of the present study were to assess the effect of the oral SIRT1 activator, SRT2104, on measures of arterial compliance in otherwise healthy cigarette smokers and patients with type 2 diabetes." (PMID 27239324, 2016). "In conclusion, it was demonstrated that type 2 diabetes conferred MDR to gastric cancer and this effect was at least partially mediated by increased Nampt and Sirt1 expression levels." (PMID 25815791, 2015). "SIRT1 regulate insulin secretion in pancreatic β cells and SIRT3 is suppressed in pancreatic islets isolated from human type 2 diabetic patients." (PMID 24073959, 2013). "The study detected a total of 11 SNP sites of the SIRT1 gene in patients with type 2 diabetes without depression and patients with type 2 diabetes comorbid depression." (PMID 39612426, 2024). "Moreover, decreased expression of miRNA-34a with resveratrol administration increased the expression of Sirtuin 1 (SIRT1), which has a protective role in reducing oxidative stress and inflammation in type 2 diabetes." (PMID 38805166, 2024). "Compared with type 2 diabetes without depression group, the expression of SIRT1 mRNA in type 2 diabetes comorbid depression group was lower, indicating that the expression of SIRT1 mRNA was related to type 2 diabetes comorbid depression." (PMID 39612426, 2024).